LINC01501 (long independently transcribed non-coding RNA 1501)
Gene: Long non-coding RNA gene on chromosome 9 (90,462,422 to 90,583,836, reverse strand). Ensembl gene ENSG00000229613.
Diseases named in the same sentence as LINC01501 in open-access papers:
LINC01501 is named in the same sentence as 1 disease in open-access papers, as found by Europe PMC text mining. Sharing a sentence is not in itself a finding about the gene and the disease.
LINC01501 shares sentences with these, for which no sentence is quoted: coronary artery disease (1 paper).